BAX (BCL2 associated X, apoptosis regulator)
Diseases named in the same sentence as BAX in open-access papers (continued):
Sharing a sentence is not in itself a finding about the gene and the disease.
Ovarian cyst (1 paper, 2021). The presence of one or more cysts of the ovary. "On the other side, the expression of Bcl-2 was significantlyelevated in these patients indicating a low rate of apoptosis in their ovarian cysts.Likewise, Isobe and Yoshimura showed that the expressions of caspase-3 and BAX wassignificantly reduced in bovine cystic ovarian disease." (PMID 33687162, 2021).
ovarian failure (1 paper, 2018). "This receptor induces expression of the apoptosis-promoting gene Bcl2-associated X protein (BAX) in oocytes, which increases the rate of oocyte apoptosis leading to earlier ovarian failure." (PMID 30481189, 2018).
pancreatic ductal adenocarcinoma (1 paper, 2022). An infiltrating adenocarcinoma that arises from the epithelial cells of the pancreas. "Treatments induced apoptosis, increased BAX/BCL-2 ratio and suppressed the expression of SOX9 and SOX18, genes shown to be significantly up-regulated in pancreatic ductal adenocarcinoma." (PMID 35408514, 2022).
paroxysmal AF (1 paper, 2025). "BAX levels correlate positively with the severity of AF, with higher levels observed in permanent AF compared to persistent and paroxysmal AF in patients with rheumatic heart disease and in persistent AF than in paroxysmal AF." (PMID 41357167, 2025).
Peptic ulcer (1 paper, 2025). The term peptic ulcer refers to acid peptic injury of the digestive tract, resulting in mucosal break reaching the submucosa. "Relative expression of the BAX gene was highly variable among the patients with peptic ulcer disease." (PMID 41614769, 2025). "Our present findings indicate that the three types of investigated tissues demonstrated similar mRNA expression levels of the BAX gene, with a slightly lower level in gastric mucosa specimens from peptic ulcer disease." (PMID 41614769, 2025). "Despite the fact that, similarly to our peptic ulcer patients, BAX gene expression was higher among patients not infected than those infected with Helicobacter pylori, this was not shown to be a statistically significant relationship (p = 0.4349)." (PMID 41614769, 2025).
Peritoneal Fibrosis (1 paper, 2023). Disorder characterized by a wide range of structural changes in PERITONEUM, resulting from fibrogenic or inflammatory processes. "BAX, PIM1, AR, and others are involved in signaling pathways such as apoptosis, cell migration, and metabolism which also involved in peritoneal fibrosis." (PMID 37266145, 2023). "Among them, MMP2, BAX, ADORA3, HIF1A, PIM1, CA12, and ALOX5 exhibited higher expression in the peritoneum with encapsulating peritoneal sclerosis compared with those in the control, which might be crucial targets of baicalein against peritoneal fibrosis." (PMID 37266145, 2023).
pituitary adenocarcinoma (1 paper, 2025). A rare adenocarcinoma with poor prognosis, arising from the adenohypophysial cells of the anterior lobe of the pituitary gland or pre-existing adenomas. "In pituitary adenocarcinomas, reduced expression of BAX and VDAC1 genes were associated with resistance to apoptosis and thus promoted tumor development." (PMID 41614769, 2025).
pituitary adenoma (1 paper, 2024). "Differential expression of VDAC1, VDAC2, BAX and BAK genes according to pituitary adenoma size and invasiveness." (PMID 39449743, 2024).
prediabetes (1 paper, 2022). "Western blot results also confirmed that the relative protein level of both actived-CASPASE3/pro-CASPASE3 and BAX/BCL-2 increased in prediabetes-FMT group, while the rescue-FMT group showed a protective effect." (PMID 35606800, 2022). "Through immunohistochemical staining, we found that the expression of apoptotic path-related BAX protein and CASPASE-3 protein were increased in prediabetes testes and epididymis, whereas the expression of BCL-2 was decreased in prediabetic testes." (PMID 35606800, 2022).
prostate (1 paper, 2020). "The caspase 3/9 activation was associated with inhibited cell proliferation, induced apoptosis, as well as increased BAX protein expression in prostate cancer." (PMID 32895397, 2020).
Pruritus (1 paper, 2019). Pruritus is an itch or a sensation that makes a person want to scratch. "In our cohort, the BCL2/BAX ratio resulted associated both with the presence of pruritus 1 month after the completion of RT treatment, and with the class of patients classified as radiosensitive by means of IRS index." (PMID 31632918, 2019). "Symptoms of pruritus resulted associated at t1 with a 0.79-fold change of XPC and with a 1.01-fold change of ZMAT3; at t2 pruritus was associated with a 0.87-fold change of ATM, and a lower BCL2/BAX ratio (respectively, 0.76- vs. 1.15-fold change)." (PMID 31632918, 2019).
pulmonary hypertensive (1 paper, 2020). "(2015) during an investigation on pulmonary hypertensive mice demonstrated that treatment with salidroside reduces RVH in treated mice and raises Caspase-3, BAX, A2aR and reduces BCL2 expression in PASMCs." (PMID 32226378, 2020).
retinal disease (1 paper, 2024). "The present and previous studies demonstrating the efficacy of M109S in mouse retinal disease models suggest that M109S has a potential to become the basis of future orally available therapeutics protecting essential cells from unwanted BAX-mediated cell death in various diseases." (PMID 38891043, 2024).
sarcopenia (1 paper, 2021). Progressive decline in muscle mass due to aging which results in decreased functional capacity of muscles. "Compared with the HF group, the expression levels of cleaved caspase-9, cleaved caspase-3, and BAX in the HF + sarcopenia group were significantly increased (P < 0.0001), but BCL2 did not change significantly (P > 0.05)." (PMID 35126176, 2021).
systemic sclerosis (1 paper, 2023). A chronic disorder, possibly autoimmune, marked by excessive production of collagen which results in hardening and thickening of body tissues. "Moreover, an increased activity of PI3K/AKT pathway in systemic sclerosis inhibits the activity of pro-apoptotic BAX protein, thus enhancing the survival of myofibroblasts in systemic sclerosis." (PMID 37606688, 2023).
temporal lobe epilepsy (1 paper, 2022). A localization-related (focal) form of epilepsy characterized by recurrent seizures that arise from foci within the temporal lobe, most commonly from its mesial aspect. "Evidence supports that both BAX and Bcl-XL genes/proteins are expressed in the neocortical region of temporal lobe epilepsy." (PMID 36515436, 2022).
thymic lymphomas (1 paper, 2024).
thymoma (1 paper, 2013). A neoplasm arising from the epithelial cells of the thymus. "In addition, other than the thymomas, the TSCCs showed lower mRNA expression of the MTCH2 gene that induces apoptosis by cooperation with tBID to facilitate BAX-mediated mitochondrial cytochrome c release." (PMID 24427739, 2013).
transitional cell carcinoma (1 paper, 2003). A malignant neoplasm arising from the transitional epithelium, usually affecting the urinary bladder, ureter, or renal pelvis.
transitional cell carcinoma of the bladder (1 paper, 2003). "In conclusion, this is the first study that has examined expression of BAX in all stages of transitional cell carcinoma of the bladder." (PMID 12592374, 2003).
trichinosis (1 paper, 2025). A parasitic helminthiasis infectious disease that involves parasitic infection of animals and humans by Trichinella spiralis, Trichinella nativa or Trichinella britovi . "The expression of BAX, a related mitochondrial apoptotic gene, during trichinosis, is crucial in regulating the differentiation, proliferation, and apoptosis of infected muscle cells during larval encapsulation." (PMID 40455365, 2025).
tubular adenoma (1 paper, 2021). A usually polypoid neoplasm arising from the glandular epithelium. "Large tubular adenomas (two cm or greater) also exhibited the highest level of BAX and consequently the lowest BCL2/BAX ratio." (PMID 34762658, 2021). "In tubular adenomas, but not in HPPs, pro-apoptotic BAX was strongly correlated with anti-apoptotic BCL2 (r = 0.48, p<0.0001), The survivin LI was highly correlated in both types of lesions with the KI-67 LI and with each of the proliferation-related analytes except for p16 in tubular adenomas." (PMID 34762658, 2021).
tubulovillous adenoma (1 paper, 2021). An epithelial neoplasm morphologically characterized by the presence of a villous and a tubular architectural pattern. "Tubulovillous adenomas also showed a strikingly low expression of pro-apoptotic BCL2 and a low pro- vs anti-apoptotic ratio, BCL2/BAX, despite small differences in the CASP3 LI." (PMID 34762658, 2021).
Tumor Lysis Syndrome (1 paper, 2025). a group of metabolic abnormalities that can occur as a complication during the treatment of cancer, most commonly after the treatment of lymphomas and leukemias. "In addition, the BAX activators could be engineered as a kill switch for cellular therapies, allowing specific induction of BAX-mediated apoptosis upon abhorrent function, e.g., cytokine storm or tumor lysis syndrome from cellular therapies expressing chimeric antigen receptors." (PMID 40911686, 2025).
vitamin D deficiency (1 paper, 2025). A nutritional condition produced by a deficiency of VITAMIN D in the diet, insufficient production of vitamin D in the skin, inadequate absorption of vitamin D from the diet, or abnormal conversion of vitamin D to its bioactive metabolites. "Moreover, vitamin D deficiency has been associated with the induction of apoptosis by downregulating anti-apoptotic genes like BCL-2 and upregulating pro-apoptotic genes like BAX, underscoring its pivotal role in OSCC carcinogenesis, morbidity, and mortality." (PMID 39582404, 2025).
ZIKV infection (1 paper, 2019). "No variation in the percentage of cells engaged in early apoptosis (BAX+) 8 h after the onset of treatment was observed when TNFα/CHX was added 2 h prior to ZIKV infection." (PMID 31671831, 2019).
cancer (570 papers, 2005 to 2026). A tumor composed of atypical neoplastic, often pleomorphic cells that invade other tissues. "For example, reduced BAX expression was associated with resistance to cisplatin treatment in cancer cell lines, and in ESCA it was associated with shortened OS time in patients treated with cisplatin." (PMID 41614769, 2025). "Studies have shown that BAX is highly expressed in a variety of cancers and is closely associated with poor prognosis in nine types of cancers." (PMID 41411247, 2025). "We investigated the expression of BAX isoforms across human cancer types using the TSVdb (TCGA Splicing Variants DB)." (PMID 40963109, 2025). "Dysregulation of the apoptotic pathway, including abnormalities in BAX expression or function, has been associated with various diseases including cancer, autoimmune diseases, cardiovascular diseases, aging and neurodegenerative disorders." (PMID 41449208, 2025). "Since it has been indicated that an increased ratio of pro-apoptotic BAX protein to anti-apoptotic Bcl-2 protein expression can be associated with apoptosis, it’s reported that 2-ME increases BAX/Bcl-2 ratio in some cancer cells." (PMID 39167288, 2024). "Intriguingly, the TMD mutation G179E in BAX promotes resistance to anti-cancer treatment by rendering cells less susceptible to Venetoclax." (PMID 39048751, 2024). "In many cancers, upregulation of HoxA1 has been associated with the suppression of apoptosis via upregulation of the anti-apoptotic genes Bcl2 and BAX, and the promotion of proliferation via upregulation of Cyclin D128,29." (PMID 38365890, 2024). "Our findings demonstrate that BAX was highly expressed in most cancers and the high expression is mostly associated with poor prognosis." (PMID 39074253, 2024). "In sum, high level of BAX was correlated with poor prognosis in many cancers, and it was a significant high-risk gene in LGG and SKCM because of their poor OS and DFS." (PMID 39074253, 2024). "Recent intensive studies of BAX/BAK shuttling, BCL-2 protein interactions and active BAX complexes have laid the foundation for developing novel strategies for cancer therapy and analyzing cellular susceptibility to apoptosis." (PMID 37728427, 2023). "The relationship between the −248G>A polymorphism of the BAX gene and clinical parameters in different types of cancer has previously been analyzed with various results." (PMID 38003498, 2023). "There are reports of loss of BAX expression in human cancers, including endometrial and colon cancers." (PMID 36342579, 2023). "The anti-cancer role of celecoxib is through various intrinsic and extrinsic pathways associated with apoptosis and the downregulation of NF-kB, caspase-9, BAX, and BCL-xL." (PMID 36661704, 2023). "Knockdown of LIPH expression effectively promoted apoptosis of cancer cells as well as upregulation of the apoptosis-associated protein BAX, increasing chemosensitivity to high gemcitabine concentrations, whereas overexpression of LIPH reversed this effect." (PMID 37990271, 2023). "They showed that the presence of the GA and AA variants of the BAX −248G>A polymorphism is associated with the risk of cancer development." (PMID 38003498, 2023). "Several reports have shown that SFN-mediated anti-cancer effects were involved in an increase of acetylated histone H3 specifically associated with the promoter region of the p21 and BAX genes in cancer cells." (PMID 36899823, 2023). "Numerous studies have shown that BA, OA, and UA cause significant fold changes in the BAX/Bcl-2 expression ratio in various cancer cells." (PMID 36615613, 2023). "The overexpression of circ_0088300 reduces the level of pro-apoptotic factors such as BCL2-associated X protein (BAX) in cancer cells and enhances migration and invasion." (PMID 35055115, 2022). "Many studies showed that BAX G(-248) A polymorphism has been associated with the risk of several cancers." (PMID 35320970, 2022).
cancer (continued). "Downregulation and loss-of-function mutation of BAX were found to be associated with chemoresistance in various cancers." (PMID 36430955, 2022). "In previous studies, overexpression of BCL2L11 and BAX have been associated with higher sensitivity of cancer cells to gefitinib." (PMID 35216325, 2022). "It has also been shown that obatoclax displayed BCL-2 associated x protein/BCL-2 antagonist killer (BAX/BAK) dependent anti-cancer efficacy by inducing mitochondrial apoptosis." (PMID 34989664, 2022). "The relationship between BAX G(-248) A gene polymorphism and clinical parameters in different types of cancer has been studied previously with various different results." (PMID 35320970, 2022). "In numerous cancers, protein expression and function are found to be affected by mutations in the promoter and coding regions of the BAX gene." (PMID 33708254, 2021). "From these, the importance of BAX protein deregulation in cancer development can stem from the loss-of-function genetic frame-shift mutations, which contribute to the prevalence of a number of solid tumors and leukemias." (PMID 34753495, 2021). "A total of 15 case-control studies (including 3460 cases and 3404 controls) of BAX -248 G>A SNP and cancer risk were included in the meta-analysis." (PMID 33906310, 2021). "For example, BAX promoter polymorphism altered its expression in chronic lymphocytic leukemia and significantly shortened the patients’ survival in many cancers." (PMID 33906310, 2021). "BAX belongs to the Bcl-2 gene family of proapoptotic proteins and frameshift mutations correlate to cancer development in different type of organs." (PMID 33572923, 2021). "Most cancer cells evade apoptosis through caspase inhibition, upregulation of Bcl-2 (in more than 50% of all types of cancers), and loss of BAX/BAK and become resistant to anticancer drugs." (PMID 33027952, 2020). "Consistently, addiction to DNA repair of BAX-protected cancer cells caused selective sensitivity to PARP inhibition." (PMID 32486514, 2020). "Deletion of VDAC2 resulted in impairment of killing of tumor cells by anti-cancer agents and the ability to suppress tumor formation, similarly to the loss of BAX." (PMID 31159324, 2019). "The relationship between BAX gene polymorphism and cancer prognosis has attracted more and more scholars’ attention." (PMID 30024563, 2018). "In the future, further extensive studies with larger sample sizes and wider range of tumor types should be performed to enrich the evidence of the association of BAX gene polymorphisms on cancer susceptibility and prognosis." (PMID 30024563, 2018). "Characteristics of the individual studies included between the BAX rs4645878 polymorphism and the risk of cancer." (PMID 30024563, 2018). "Overall, there was null collection of BAX polymorphisms in the allele frequencies or other genotype models with overall cancer risk." (PMID 30024563, 2018). "Deleting VDAC2 phenocopied the loss of BAX in impairing both the killing of tumor cells by anti-cancer agents and the ability to suppress tumor formation." (PMID 30478310, 2018). "Characteristics of the individual studies included between the BAX rs4645878 polymorphism and the prognosis of cancer." (PMID 30024563, 2018).